MUC21 (mucin 21, cell surface associated)
Synonyms: MUC-21; C6orf205; bCX31G15.2; KMQK697
Tractability: Antibody: UniProt places it where antibodies can reach, with high confidence; its Gene Ontology location is reachable by antibodies, with high confidence; UniProt predicts a signal peptide or a membrane-spanning region.
Gene: Protein-coding gene on chromosome 6 (30,983,718 to 30,989,903, forward strand). Ensembl gene ENSG00000204544.
Subcellular location: Cell membrane
Pathways (Reactome):
Disease: Defective C1GALT1C1 causes TNPS; Defective GALNT12 causes CRCS1; Defective GALNT3 causes HFTC
Metabolism of proteins: O-linked glycosylation of mucins; Termination of O-glycan biosynthesis
Immune System: Dectin-2 family
Gene Ontology:
Biological process: negative regulation of cell-cell adhesion
Cellular component: Golgi lumen; plasma membrane
Genetic constraint (gnomAD): Loss-of-function variants: 7 observed, 7.35 expected, observed/expected ratio (o/e) 0.95, 90% interval 0.54 to 1.7. That is too few expected variants to judge how well the gene tolerates losing a copy. Missense variants: 437 observed, 590.16 expected, observed/expected ratio (o/e) 0.74, 90% interval 0.68 to 0.8. Synonymous variants: 173 observed, 229.57 expected, observed/expected ratio (o/e) 0.75, 90% interval 0.67 to 0.86.
Homologues: Orthologues: chimpanzee MUC21 (20% identical).
Diseases named in the same sentence as MUC21 in open-access papers:
MUC21 is named in the same sentence as 50 diseases in open-access papers, as found by Europe PMC text mining. Sharing a sentence is not in itself a finding about the gene and the disease. The quoted sentences say what the papers report.
lung adenocarcinoma (11 papers, 2019 to 2024). A carcinoma that arises from the lung and is characterized by the presence of malignant glandular epithelial cells. "Recent studies have shown that MUC21 is the main cause of the difference between lung adenocarcinoma and lung squamous cell carcinoma." (PMID 38933439, 2024). "Recent studies have found that MUC21 is expressed in lung adenocarcinoma, and is associated with the invasive behavior of tumor cells." (PMID 38933439, 2024). "Additionally, MUC21, a gene previously associated with lung adenocarcinoma, was also upregulated in Ghanaians with severe COVID-19." (PMID 38375062, 2024). "The latest research indicates that specific glycosylated MUC21 may be involved in the development of lung adenocarcinoma with EGFR mutations." (PMID 38933439, 2024). "This suggests that MUC21 may be associated with the formation of micropapillae structures in lung adenocarcinoma." (PMID 38933439, 2024). "We investigated the significance of MUC21 in EGFR-mutated lung adenocarcinoma (LADC)." (PMID 30973916, 2019). "Moreover, the development of EGFR-mutated lung adenocarcinomas may also be associated with MUC21 protein, which exhibits specific glycosylation states." (PMID 38933439, 2024). "Further studies are needed to elucidate the specific mechanisms by which MUC21 contributes to the pathogenesis of lung adenocarcinoma and explore its potential as a biomarker for predicting disease progression and treatment response." (PMID 38933439, 2024). "Among them, mucin family member MUC21 is highly expressed in glioblastoma, thyroid cancer, melanoma, and lung adenocarcinoma, and plays a significant role in their development." (PMID 38933439, 2024). "Research has shown that MUC21 is expressed in esophageal squamous cell carcinoma, lung adenocarcinoma, glioblastoma, thyroid cancer, melanoma, and various other malignant tumors in distinctive manner." (PMID 38933439, 2024). "MUC21 is a unique immunohistochemical biomarker that distinguishes between lung adenocarcinomas and epithelial mesotheliomas." (PMID 38933439, 2024). "In summary, MUC21 exhibits specific expression in tumor types such as lung adenocarcinoma, melanoma, and glioblastoma, making it a potential candidate for the diagnosis, treatment, and prognosis of these tumors." (PMID 38933439, 2024). "It was found that the expression of MUC21 was significantly different in lung adenocarcinoma and epithelial mesothelioma." (PMID 38933439, 2024). "In summary, MUC21 expression can affect the formation of micropapillary structures, thereby promoting the development of lung adenocarcinoma." (PMID 38933439, 2024). "The biological activities of MUC21, including its involvement in the progression of EGFR-mutated lung adenocarcinomas or its ability to confer resistance to apoptosis, are thought to rely on specific glycosylation patterns." (PMID 37858248, 2023). "This is recently shown for MUC21 overexpression as influencing the development of lung adenocarcinoma and TFF1 influencing epithelial-mesenchymal transition." (PMID 33308144, 2020). "Specifically, lung adenocarcinoma exhibits upregulation of genes related to mucin O-chain glycosylation, suggesting that the detection of MUC21 expression may serve as a targeted treatment for lung adenocarcinoma." (PMID 38933439, 2024). "Ahmad and colleagues also discovered that MUC21 shows high levels of expression in the micropapillary structures of lung adenocarcinoma, especially during the transition from pure lepidic to micropapillary tumors through the presence of low papillary lepidic lesions." (PMID 38933439, 2024). "The expression of MUC21 is low in epithelial mesothelioma, but high in lung adenocarcinoma." (PMID 38933439, 2024). "Correlation between MUC21 expression and pathological factors in EGFR-mutated lung adenocarcinomas." (PMID 30973916, 2019). "Relationships between MUC21 expression and clinicopathological factors in lung adenocarcinomas." (PMID 30973916, 2019).
lung adenocarcinoma (continued). "Moreover, a number of studies have shown that MUC21 is involved in the invasion and development of malignant tumors such as lung adenocarcinoma, melanoma and glioblastoma, and it has become a promising therapeutic target for the development of targeted therapies." (PMID 38933439, 2024). "The steric hindrance-mediated inhibition of TCR and peptide-MHC engagement by MUC21 allows cancer cells to evade T cell mediated immune surveillance, which may help explain why MUC21 is expressed in incohesive-type lung adenocarcinoma that is prone to metastasis." (PMID 37858248, 2023). "In conclusion, the discovery of MUC21 as a negative marker for mesothelioma and lung adenocarcinoma represents a significant advancement in the field of cancer research and holds promise for improving patient outcomes in the future." (PMID 38933439, 2024). "We also found that some GRGs specifically associated with different tumor types are upregulated when compared to normal cells, as is the case of MUC21 in lung adenocarcinoma and GALNT6 and MUCL1 in non-TNBC breast cancer." (PMID 38384845, 2024). "Recently, a discovery was made highlighting the potential of MUC21 as a new negative marker for distinguishing between mesothelioma and lung adenocarcinoma." (PMID 38933439, 2024). "Further, we recently reported a characteristically high MUC21 protein expression in cancer cells of patients with incohesive-type lung adenocarcinoma as opposed to other, cohesive-type lung adenocarcinomas." (PMID 35410995, 2022). "MUC21 was more recently discovered in lung adenocarcinoma and has not been described in pancreatic pathologies." (PMID 33182511, 2020). "Recent studies have shown that MUC21 acts a negative marker for epithelioid mesothelioma and that MUC21 proteins with a specific glycosylation status may be involved in the progression of EGFR-mutated lung adenocarcinomas." (PMID 35743163, 2022).
COVID-19 (5 papers, 2020 to 2024). A disease caused by infection with severe acute respiratory syndrome coronavirus 2. "It is interesting to note that MUC21 mRNA expression was only selected as a variable associated with COVID-19 severity, whereas MUC13, MUC4, and MUC6 mRNA expression were uniquely identified as variables indicative for COVID-19 presentation." (PMID 34448730, 2021). "A significant increase in MUC13 mRNA expression was seen in the COVID-19 patient groups compared with healthy controls and the mild non–COVID-19 group, whereas MUC21 mRNA expression was only significantly increased in the mild COVID-19 patient group." (PMID 34448730, 2021).
lung carcinoma (5 papers, 2020 to 2025). "We further examined the inhibitory effects of MUC21 on antibody-mediated NK cytotoxicity using A549 lung cancer cells, which lack endogenous MUC21." (PMID 37858248, 2023). "Bioinformatics analysis revealed elevated MUC21 expression in lung cancer, which correlated with reduced infiltration and activation of cytotoxic immune cells." (PMID 37858248, 2023). "The co-localization of MUC22 and MUC21 in the mucin gene cluster on chromosome 6p21.3 suggests a link between these genes in lung cancer progression and heterogeneity." (PMID 37858248, 2023). "MUC16 and MUC21 exhibit specific expression patterns and functions in lung cancer." (PMID 40655139, 2025). "Regarding MUC21, the literature on its expression in lung cancer is scarce, but preliminary findings suggest that its upregulation is associated with diminished infiltration and activation of cytotoxic immune cells, possibly contributing to immune evasion mechanisms in lung cancer." (PMID 40655139, 2025). "Moreover, our bioinformatics analysis revealed an increased expression of MUC21 in lung cancer, which correlated with decreased immune cell infiltration." (PMID 37858248, 2023). "Moreover, it seems that MUC16, MUC21 and MUC5B showed high mutation rates, mRNA expression and close relations to tumor immune infiltration may be still a great target for lung cancer target and immune therapy." (PMID 32807223, 2020). "Extensive research has been conducted on the role of MUC family genes in lung cancer, particularly MUC1 and MUC21." (PMID 41409294, 2025).
breast carcinoma (4 papers, 2021 to 2024). "Mucin 21 (MUC21) is a unique transmembrane-type mucin, found in an endeavor to identify mouse epiglycanin, a mammary carcinoma-associated mucin." (PMID 35410995, 2022).
melanoma (3 papers, 2023 to 2024). A malignant, usually aggressive tumor composed of atypical, neoplastic melanocytes. "While the exact functioning of MUC21 is not yet fully understood, it is essential in the progression of thyroid cancer and melanoma and can serve as a significant prognostic indicator." (PMID 38933439, 2024). "Despite its short cytoplasmic tail of 49 amino acids, MUC21 has been reported to be associated with the STAT3/AKT and hedgehog pathways in glioblastoma and melanoma, respectively, leading to tumor cell proliferation and migration." (PMID 37858248, 2023). "In addition to inducing glioblastoma survival and migration through STA/AKT pathway, MUC21 also regulates SLITRK5 gene expression, thereby controlling Hedgehog signaling pathway to promote melanoma progression." (PMID 38933439, 2024).
thyroid cancer (3 papers, 2023 to 2024). "Furthermore, the expression of MUC21 is significantly linked to the outlook of individuals with thyroid cancer, identified as a potential marker for predicting prognosis." (PMID 38933439, 2024). "Recent research has revealed a noteworthy increase in the expression of MUC21 in thyroid cancer tissues." (PMID 38933439, 2024). "MUC21 can also be used as a specific phagocytosis regulatory factor to predict the recurrence and efficacy of thyroid cancer." (PMID 38933439, 2024).
glioblastoma (2 papers, 2023 to 2024). The most malignant astrocytic tumor (WHO grade IV). "Moreover, through the development of specific antibodies targeting the MUC21 cytoplasmic tail, researchers have also discovered the expression of MUC21 in the cytoplasm of glioblastoma cells." (PMID 38933439, 2024).
lymph node metastasis (2 papers, 2025 to 2026). "Low MUC21 expression correlated with pathological lymph node metastasis, poor tumor differentiation, and reduced survival." (PMID 41959914, 2026). "In contrast, other mucins such as MUC1 and MUC21 have been reported in LUAD and NSCLC, with roles in immune modulation and EGFR mutation-specific expression patterns, but their associations with lymph node metastasis remain less clearly defined." (PMID 41409294, 2025).
mesothelioma (2 papers, 2022 to 2024). A usually malignant and aggressive neoplasm of the mesothelium which is often associated with exposure to asbestos. "MUC21 is a novel transmembrane MUC that could be used as a negative immunohistochemical marker to differentiate mesothelioma from LUAD." (PMID 36059804, 2022).
squamous cell carcinoma (2 papers, 2023 to 2024). A carcinoma arising from squamous epithelial cells. "A glycoform of MUC21 with extended carbohydrate chains was found in suprabasal cells and serves as a marker for differentiation in squamous cell carcinoma, which suggests another possible marker for esophageal differentiation." (PMID 37692891, 2023).
asthma (1 paper, 2018). "Since overproduction of mucins is associated with common respiratory diseases including COPD, asthma and cystic fibrosis, MUC21 is a biological plausible gene and further investigations into the inverse association between DNA methylation at cg06126421 and the expression of MUC21 are warranted." (PMID 30390659, 2018).
cataract (1 paper, 2016). Partial or complete opacity of the crystalline lens of one or both eyes that decreases visual acuity and eventually results in blindness. "While the LEMD2 variant cosegregated with cataracts in 84 family members (including 17 affected individuals), the MUC21 variant did not." (PMID 26788539, 2016). "While the LEMD2 variant cosegregated perfectly with cataracts, the MUC21 variant did not." (PMID 26788539, 2016). "Contrastingly, MUC21 c.665delC does not cosegregate perfectly with cataracts, making it less likely that MUC21 is the cataract gene." (PMID 26788539, 2016). "Contrastingly, MUC21 c.665delC does not cosegregate perfectly with cataracts; one healthy individual (AR‐900‐57) is also homozygous for MUC21 c.665delC." (PMID 26788539, 2016).
colorectal cancer (1 paper, 2017). A primary or metastatic malignant neoplasm that affects the colon or rectum. "Our results demonstrate de novo expression of certain mucins in cancer tissues, including MUC21 in colorectal cancers." (PMID 28978023, 2017). "Examining de novo expression of mucins to serve as biomarkers led to the finding of MUC21 in colorectal cancers, although the increase in mRNA is very low." (PMID 28978023, 2017).
depression (1 paper, 2020). "In the bivariate meta-analyses of the broad depression phenotype and self-reported MDD, three loci (NEGR1, MAT2B, MUC21) reached genome-wide significance and all were replicated." (PMID 30626913, 2020).
esophageal squamous cell carcinoma (1 paper, 2024). Esophageal squamous cell carcinoma (ESCC) is a type of esophageal carcinoma (EC) that can affect any part of the esophagus, but is usually located in the upper or middle third. "Recent research has found that the MUC21 glycoform can differentiate between esophageal squamous epithelial cells and esophageal squamous cell carcinoma, and is downregulated in laryngeal squamous cell carcinoma." (PMID 38933439, 2024). "Research has indicated that the alteration in the MUC21 glycosylation can be used to differentiate between esophageal squamous epithelium and esophageal squamous cell carcinoma." (PMID 38933439, 2024). "In summary, further research on the regulation of the MUC21 glycoform could potentially provide new strategies for the diagnosis and treatment of esophageal squamous cell carcinoma." (PMID 38933439, 2024).
glioma (1 paper, 2024). A benign or malignant brain and spinal cord tumor that arises from glial cells (astrocytes, oligodendrocytes, ependymal cells). "Specific mucins that have now been implicated in glioma include MUC1, MUC4, MUC15, MUC16, MUC17, MUC18 and MUC21." (PMID 39767713, 2024). "While MUC1, MUC4, MUC15, MUC16, MUC17, and MUC21 are all potential candidate biomarkers for glioma, the extensive research on MUC1 and the current clinical application of MUC16 in ovarian cancer highlights their promise as therapeutics for glioma." (PMID 39767713, 2024).
metastatic melanoma (1 paper, 2024). A melanoma that has spread from its primary site to another anatomic site. "Previous studies have shown that the presence of MUC21 is elevated in metastatic melanoma tissues, and individuals with high levels of MUC21 tend to have poorer overall survival rates." (PMID 38933439, 2024).